DYTN (dystrotelin)
Tractability: Antibody: UniProt places it where antibodies can reach, with medium confidence; its Gene Ontology location is reachable by antibodies, with medium confidence.
Gene: Protein-coding gene on chromosome 2 (206,651,621 to 206,721,570, reverse strand). Ensembl gene ENSG00000232125.
Subcellular location: Cell membrane
Gene Ontology:
Molecular function: zinc ion binding
Biological process: synaptic signaling
Cellular component: plasma membrane; synapse
Genetic constraint (gnomAD): Loss-of-function variants: 72 observed, 65.96 expected, observed/expected ratio (o/e) 1.09, 90% interval 0.9 to 1.33. The upper end of that interval is the gene's LOEUF score, 1.33, which puts it in group 5 of 6, group 1 being the genes least tolerant of losing a copy. Missense variants: 696 observed, 689.86 expected, observed/expected ratio (o/e) 1.01, 90% interval 0.95 to 1.07. Synonymous variants: 240 observed, 250.94 expected, observed/expected ratio (o/e) 0.96, 90% interval 0.86 to 1.06.
Homologues: Orthologues: macaque DYTN (94% identical), chimpanzee DYTN (90% identical), dog DYTN (72% identical), pig DYTN (72% identical), rabbit DYTN (71% identical), rat Dytn (59% identical), mouse Dytn (59% identical), zebrafish dytn (29% identical). Paralogues in human: PLEC (16% identical), SPTBN5 (16% identical), SYNE1 (16% identical), SPTBN1 (16% identical), SPTB (16% identical), SPTBN2 (15% identical), DMD (15% identical), MICAL3 (15% identical), SYNE2 (15% identical), DST (15% identical), MACF1 (15% identical), UTRN (15% identical), and 24 more.
Diseases named in the same sentence as DYTN in open-access papers:
DYTN is named in the same sentence as 10 diseases in open-access papers, as found by Europe PMC text mining. Sharing a sentence is not in itself a finding about the gene and the disease. The quoted sentences say what the papers report.
Dystonia (1 paper, 2022). An abnormally increased muscular tone that causes fixed abnormal postures. "A total of seven hub genes were identified in BY chickens, among which PPFIA4 is a prognostic monitoring indicator of thyroid cancer, lipoma and epilepsy, and DYTN is associated with Leiber visual atrophy, dystonia and lymphatic malformations." (PMID 36557693, 2022).
encephalitis (1 paper, 2021). An acute inflammatory process affecting the brain parenchyma. "The exact role of DYTN is uncertain, but the gene has previously been associated with nephrolithiasis and encephalitis." (PMID 33947878, 2021).
tumour (1 paper, 2024). "The CpGs constituting the FCC were primarily associated with the two known aging genes ELOLV2 and KLF14, linked to metabolism, which were hypermethylated, followed by a tumour suppressing gene RNF180, and DYTN, a gene with unknown function, that were both hypomethylated." (PMID 39695947, 2024).
DYTN also shares sentences with these, for which no sentence is quoted: epilepsy (1 paper); lipoma (1); lymphatic malformation (1); nephrolithiasis (1); osteoarthritis (1); spastic ataxia (1); thyroid cancer (1).